TERT (telomerase reverse transcriptase)
Diseases named in the same sentence as TERT in open-access papers (continued):
Sharing a sentence is not in itself a finding about the gene and the disease.
cancer (continued). "The increased cancer incidence in TERT KO mice could be explained by telomere loss in stem cells compromising the immune system, thereby allowing more cancer cells to avoid immune surveillance." (PMID 33257697, 2020). "In addition, TERT is highly conserved, also in tumors, with cancer-associated mutations occurring mainly in the promoter region, which opens a possibility to make this vaccine basically universal." (PMID 32570805, 2020). "Enhancement of TERT transcription is the principal cause of its cancer-specific activation and studies on several tumors support the concept that noncoding mutations within promoter regions of TERT may act as a driver." (PMID 33113965, 2020). "Using a next-generation sequencing technique, the authors performed a comprehensive methylation analysis and revealed a TERT hypermethylated oncological region (THOR) defining a 433 bp genomic region within the TERT promoter as a cancer-associated epigenetic mechanism of TERT upregulation." (PMID 32722302, 2020). "Many other somatic mutations were detected that occur in the TERTp in cancer, although less frequently than C228T and C250T and they also may contribute to increased TERT transcription." (PMID 33329574, 2020). "Furthermore, in cancer cells, TERT upregulation can be achieved by TERT amplifications, TERT promoter mutations, and TERT promoter methylation." (PMID 33053763, 2020). "Thus, a mechanistic elucidation underlying cancer-specific activation of the TERT transcription is of intense interest to cancer research." (PMID 31285550, 2019). "Moreover, risk of regional failure, progression, and death were independently associated with high levels of TERT thus confirming previous data showing that TERT levels in cancer tissue increase with the aggressiveness of the disease." (PMID 31772219, 2019). "The TERT promoter mutation rate varies significantly from undetectable to more than 90% among studied human malignancies, and it remains poorly understood what cause such differential mutation distributions among different types of cancer." (PMID 31285550, 2019). "The hypermethylated TERT promoter has also been shown to be unique to human cancer and might serve as a diagnostic biomarker." (PMID 31285550, 2019). "For example, it has been extensively shown the crucial role that MLL3/MLL4/COMPASS-like family of histone H3 lysine 4 (H3K4) monomethyltransfereases have in cancer and also the role that TERT promoter mutations leading to upregulation of telomerase expression observed in human cancer." (PMID 31671657, 2019). "Importantly, reactivation of TERT expression is also associated with TERT-promoter mutations, currently found in many types of cancers." (PMID 32082377, 2019). "An average of 27% tumors was observed to bear TERT promoter mutations in the TCGA pooled cohort, and they have so far been the most common mutations identified in non-coding regulatory regions in human cancer." (PMID 31285550, 2019). "Therefore, in this study, we performed a comprehensive meta‐analysis including the latest and relevant articles to explore the association between the TERT rs10069690 polymorphism and cancer risk." (PMID 31454181, 2019). "However, a number of problems (such as unstable TERT mRNA and enzymatic activity) impede reliable utility of the direct TERT expression or telomerase activity assay as routine cancer diagnostic or disease monitoring tools." (PMID 31284662, 2019). "A single nucleotide polymorphism (SNP) rs10069690 located in intron 4 of TERT, has been hypothesized to be associated with the risk of cancers development by many researchers, however, the results are conflicting and heterogeneous." (PMID 31454181, 2019). "The relevance of BRD4 in controlling TERT expression selectively in presence of cancer-associated promoter mutations, seems to suggest that inhibition of BRD4 by BETi could represent an alternative and more selective inhibition of telomerase." (PMID 30466442, 2018).
cancer (continued). "Indeed, point mutations in the telomerase (TERT) promoter, which increase TERT expression, are the most commonly identified non-coding mutations found in human cancer." (PMID 30067734, 2018). "Disruption of the TERT promoter is likely to cause the dysregulation of the telomerase reverse transcriptase (TERT) expression, which plays important roles in cancer development due to its diverse telomere-independent functions in Wnt pathway signaling, cell proliferation, and DNA-damage repair." (PMID 30521023, 2018). "It has been reported that the functional telomerase reverse transcriptase (TERT) rs2853669 polymorphism might contribute to different types of human cancer." (PMID 29534075, 2018). "We suggested that TERT gene may have association with cancers and disease by influencing the balancing the telomere length." (PMID 29507683, 2018). "Indeed, as in many human cancer cell lines, the majority of TERT mRNA in HeLa cells is reportedly the beta deletion variant, which codes for enzymatically inactive protein." (PMID 30517099, 2018). "We next investigated whether BRAF V600E and TERT promoter mutations cooperatively affected TERT expression in a panel of human cancer cells with various BRAF and TERT genotypes." (PMID 29422527, 2018). "Transcriptional factors ETS1/2 and p52 synergize downstream of non-canonical NF-κB signaling to drive reactivation of the −146C>T mutant TERT promoter in multiple cancer types, but the mechanism underlying this cooperativity remains unknown." (PMID 30093619, 2018). "Thus far, the most notable example of noncoding variations in cancer is from the identification of driver mutations in the promoter regions of the telomerase reverse transcriptase (TERT) gene." (PMID 30577431, 2018). "Several studies indicate that TERT rs2736100 polymorphism, located at intron 2 of the TERT gene, may modify telomere homeostasis and is mostly related to different types of cancers." (PMID 29967663, 2018). "Somatic mutations in the TERT promoter are found across multiple cancer types." (PMID 30073017, 2018). "Common somatic TERT promoter mutations were recently discovered in many human cancers." (PMID 29439385, 2018). "Indeed, many different human cancer types show mutations in either the promotor region or coding regions of the telomerase catalytic subunit TERT gene." (PMID 30114189, 2018). "These TERT promoter mutations are amongst the most common non-coding mutations in cancer." (PMID 29616301, 2018). "Furthermore, the presence of TERT promoter mutations has been shown to decrease cancer-specific survival and increased disease stage." (PMID 30099580, 2018). "Systematic analysis of the Cancer Genome Atlas database revealed that methylation of the TERT promoter region is one of the most prevalent markers associated with TERT expression in human cancers, in addition to the discovery of common somatic point mutations in the TERT promoter." (PMID 29439385, 2018). "Altogether, these studies show that mutations within the promoter region of the TERT gene allow an overall increase in production and therefore activity of telomerase, which accounts for yet another explanation of how cancer cells maintain lengthy telomeres (Liu, Yuan & Xu, 2016)." (PMID 29922517, 2018). "Thus, we performed a meta-analysis screening of all relevant published data to clarify the association between the TERT rs2853669 polymorphism and cancer risk." (PMID 29534075, 2018). "Activating somatic mutations of the TERT promoter have been reported in various cancers." (PMID 29100407, 2017). "In addition, single nucleotide polymorphisms (SNPs) in the TERT rs2736098 and rs2736100 are significantly associated with cancer susceptibility." (PMID 28416747, 2017). "The central role of TERT in oncogenesis has also promoted studies of cancer susceptibility and association with single nucleotide polymorphisms (SNPs) in the TERT locus, and the accumulated evidence indeed suggests the association between cancer risk and TERT SNPs." (PMID 28416747, 2017).
cancer (continued). "Thus, we performed an updated meta-analysis to more precisely assess the TERT rs2736100 polymorphism-cancer association, including 72 studies derived from 61 articles with 269,720 total subjects." (PMID 28418878, 2017). "These authors have consequently suggested that inhibitors could be designed to hinder TERT transcription in cancer cells with these mutations." (PMID 29108273, 2017). "An increasing number of studies suggest that somatic mutations (e.g., -124C>T and -146C>T) and single nucleotide polymorphisms (SNPs) within the TERT promoter (TERTp) could influence the susceptibility and prognosis of human cancers." (PMID 28881610, 2017). "Collectively, the germline TERT genetic background may significantly affect the onset of TERT promoter mutations in HCCs, which contributes to better understandings of the mechanism underlying cancer-related telomerase activation." (PMID 28416747, 2017). "Moreover, four cancer-associated genes showed a high frequency of copy number gain in both datasets (i.e. TERT, FCGR2B, CD79B and PRKAR1A)." (PMID 29371938, 2017). "TERT gene encodes for the catalytic subunit of the telomerase reverse transcriptase which is an RNA-dependent DNA polymerase highly expressed in germ cells, in stem cells and in cancer cells." (PMID 28529542, 2017). "Notably, genetic alterations in the proximal promoter of the telomerase reverse transcriptase gene (TERT) are significantly associated with many cancer types." (PMID 28881610, 2017). "The sensitivity of TERT promoter mutation for the purpose of predicting cancer risk is low in the indeterminate category, so testing for this mutation may not be cost-effective." (PMID 29085338, 2017). "Heterogeneity was detected amongst studies with respect to the association between the TERT rs2736100 polymorphism and overall cancer risk (homozygous model: P<0.001; heterozygous model: P<0.001; dominant model: P<0.001; recessive model: P<0.001; and allele contrast model: P<0.001)." (PMID 28418878, 2017). "Our results confirm that the TERT rs2736100 polymorphism confers increased overall cancer risk." (PMID 28418878, 2017). "Besides long-range enhancer-promoter looping mechanisms, oncogenic signaling pathways such as the RAS-ERK pathway can regulate TERT reactivation at mutant TERT promoters in cancers harboring BRAF mutations." (PMID 28264499, 2017). "The present meta-analysis, comprising 108,248 cases and 161,472 controls, found that the TERT rs2736100 polymorphism increased overall cancer risk by 16–39%, suggesting that this SNP may contribute to carcinogenesis." (PMID 28418878, 2017). "In addition, multiple independent variants at the TERT locus are associated with telomere length and risk of malignant tumors." (PMID 28060765, 2017). "Hence, in contrast to other neuroectodermal derived malignant neoplasms, TERT promoter mutations occur infrequently in MPNST." (PMID 28454108, 2017). "For example, mutations in the promoter of the telomerase reverse transcriptase (TERT) gene have been identified as pan-cancer driver mutations that function by creation of a de novo transcription factor binding site upstream of TERT, resulting in TERT mRNA upregulation." (PMID 28056774, 2017). "In contrast, TERT genetic alterations, which occur in around 55% of all PTs and include TERT promoter hotspot mutations and rare TERT gene amplification, are more frequent in malignant tumors." (PMID 28267263, 2017). "We found that the TERT rs2736098 polymorphism was associated with risk of cancer in overall analysis (AA vs. GG: OR = 1.26, 95% CI = 1.09–1.47; AA vs. AG/GG: OR = 1.22, 95% CI = 1.09–1.36; AA/AG vs. GG: OR = 1.13, 95% CI = 1.02–1.24; A vs. G: OR = 1.11, 95% CI = 1.04–1.20)." (PMID 29221218, 2017). "Notably, our data suggest that the mechanism by which ZNF148 influences TERT is similar for cancer types in which the C-allele of rs36115365 contributes to increased risk, or alternatively to disease protection." (PMID 28447668, 2017).
cancer (continued). "These lines of evidence suggested that TERT rs2736098 polymorphism may have different effects in different cancer types." (PMID 29221218, 2017). "Therefore, it is of significant clinical benefit to develop a non-invasive and sensitive test that determines the TERT promoter mutation status in cancer patients." (PMID 29108273, 2017). "On the other hand, RAS and K601E mutations alone carry a low-to-moderate cancer risk (53% for the former and 25% for the latter), so the identification of a TERT promoter mutation might still be useful to the clinician in the setting of indeterminate nodules." (PMID 29085338, 2017). "In such a particular setting, however, where it remains mandatory to recognize rare cancers with an aggressive behavior, testing for TERT promoter mutations might still prove its worth, particularly in the preoperative setting." (PMID 29085338, 2017). "In addition, the TERTp mutations are well established to increase TERT expression and its activity, with a tissue-specific distribution in several cancers." (PMID 28881610, 2017). "Mechanistically, TERT was shown to indirectly associate with promoters of NFκB target genes interleukin (IL)-6, tumor necrosis factor (TNFα) and IL-8, which are critical for inflammation and cancer progression, to increase expression." (PMID 26846696, 2016). "Little is known about the mechanism underlying the TERT promoter hypermethylation in cancer." (PMID 26870890, 2016). "We genotyped telomerase reverse transcriptase (TERT) rs2736100 variants, the SNP associated with a risk of multiple-types of cancer, in patients with UTUC (n = 212) and evaluated the relationship between the rs2736100 and UTUC risk by comparing to 289 healthy controls." (PMID 26934125, 2016). "Likely, different genetic susceptibility and/or environment exposure may contribute to such disparities in TERT promoter mutations observed in same types of cancer from different geographical areas." (PMID 27438857, 2016). "Increased TERT promoter activity and TERT expression is a hallmark of most cancer types." (PMID 27240403, 2016). "The nucleotide change at nt −124 was the most frequent representing 96.9% of all TERT mutations, while the mutation at nt −146 was found in only two cancer cases from male patients older than 65 years, of which one was positive for HCV and the second positive for HBV." (PMID 27276713, 2016). "This may be due to e.g. specific mutations in the TERT promoter that are common in certain cancer types, as initially described in melanoma." (PMID 26870890, 2016). "Moreover, other alterations which result in telomere maintenance in cancer such as TERT promoter mutations and the presence of alternative lengthening of telomeres are rarely observed in PCa." (PMID 27437772, 2016). "However, the discovery of frequent mutations in the promoter of TERT highlighted a possible mechanism of catalytic subunit of reverse transcriptase expression in cancer cells." (PMID 27449293, 2016). "Although lymphocytes are known to be a cell type characterized by high telomerase activity throughout their life cycle, lymphoid malignancies are associated with elevated TERT expression like the majority of cancers, suggesting a requirement for persistent TERT activity in transformed cells." (PMID 27792139, 2016). "Detection of cancer-specific TERT mutations in patients with low serum AFP may thus complement the AFP assay which has insufficient sensitivity and specificity for early diagnosis of HCC." (PMID 27056898, 2016). "These TERT promoter mutations stimulate TERT transcriptional activity in cancer cells." (PMID 26857243, 2016). "TERT promoter mutations are evidently selected for cancer progression or invasion." (PMID 27438857, 2016). "In addition, the TERT promoter mutation detection has demonstrated usefulness in cancer diagnostics and outcome prediction, but the obtained data are still preliminary and inconclusive, and more large-scale validation studies are definitely required." (PMID 27438857, 2016).
cancer (continued). "By contrast, cancer-initiating cells originating from cells with low self-renewing capability may require TERT promoter mutations to overcome the short-telomere-dependent proliferative barrier." (PMID 27323951, 2016). "Different cancer types have various TERT promoter mutation frequencies." (PMID 26575952, 2016). "Activating mutations in TERT promoter have been found as drivers in multiple types of cancer." (PMID 27311963, 2016). "Aberrant TERT expression results in a limitless proliferative potential, a hallmark of cancer." (PMID 26992833, 2016). "Indeed, CpG hypermethylation of the TERT promoter has been demonstrated in some other cancer types and associated with increased TERT expression and patient outcome." (PMID 26870890, 2016). "The TERT gene encodes the catalytic subunit of telomerase, known for its critical role in maintaining telomere ends and the increased telomerase activity frequently seen in human cancers." (PMID 27579533, 2016). "TERT plays a key role in oncogenesis via both telomere lengthening-dependent and independent activities, and it is thus not surprising to observe an intimate association between its SNPs and cancer risk." (PMID 26934125, 2016). "Interestingly, the frequency of the TERT promoter mutation increased in advanced or progressive cancer." (PMID 27438857, 2016). "It remains to be determined why cancer cells express catalytically inactive TERT isoforms and whether expression of specific isoforms would change in cancers harboring promoter mutations." (PMID 26846696, 2016). "While TERT expression is low in most somatic cells, endothelial cells represent an established exception and associations observed for differential expression between carcinoma and normal mucosa is a likely extension of that observation." (PMID 27627813, 2016). "TERT was reported to be implicated in initiation and self-renewal of cancer stem cells." (PMID 26143634, 2015). "Moreover, the presence of TERT promoter mutations strongly demonstrates the mechanistic relevance of telomere biology in cancer progression, which is predicated on the finding of shorter telomeres in tumors with mutations than without mutations." (PMID 25797251, 2015). "Recent studies have reported that TERT is implicated in the modulation of cancer stem cells." (PMID 26143634, 2015). "Cancer cells often contain mutations in the promoter of the gene that encodes TERT." (PMID 26194807, 2015). "However, over-expression of TERT enables telomere renewal, which is necessary for cellular immortalisation, a hallmark of cancer." (PMID 26356674, 2015). "Furthermore, telomerase activity in the differentiated cells with TERT promoter mutations was very similar to the level of activity in cancer cell lines, which further illustrates the powerful effects of these promoter mutations." (PMID 26194808, 2015). "However, the impacts of TERT variants on cancer progression and treatment efficacy have remained controversial." (PMID 26020272, 2015). "Initially, the only regulatory mutations that are common in many cancers were reported in the core promoter of the telomerase reverse transcriptase (TERT) gene, which increase TERT transcription through creation of binding motifs for E-twenty six/ternary complex (Ets/TCF) transcription factors." (PMID 26416425, 2015). "In addition, the presence of TERT promoter mutations has also been demonstrated to be associated with poor patient outcome in several types of cancer including BC." (PMID 25474136, 2014). "Clinical observations suggest that TERT promoter mutations may predict outcomes and associate with aggressive diseases in a number of cancer types." (PMID 25301727, 2014). "Mutations in the coding regions of TERT can affect telomerase activity and telomere length, resulting in severe clinical phenotypes, including bone marrow failure syndromes and a substantial increase in cancer frequency." (PMID 25007268, 2014).